CA5BP1 (carbonic anhydrase 5B pseudogene 1)
Synonyms: PRO2325; formerly CA5BL; CA5BP
Gene: Transcribed unprocessed pseudogene on chromosome X (15,681,053 to 15,703,192, forward strand). Ensembl gene ENSG00000186312.
Diseases named in the same sentence as CA5BP1 in open-access papers:
CA5BP1 is named in the same sentence as 1 disease in open-access papers, as found by Europe PMC text mining. Sharing a sentence is not in itself a finding about the gene and the disease.
CA5BP1 shares sentences with these, for which no sentence is quoted: cancer (1 paper).